CCL2 (C-C motif chemokine ligand 2)
Diseases named in the same sentence as CCL2 in open-access papers (continued):
Sharing a sentence is not in itself a finding about the gene and the disease.
tumor (continued). "Therefore, it is plausible that CCL2 signalling may have dual context-dependent effects in tumourigenesis: promoting metastasis of established primary tumours, but performing tumour immune-surveillance in neo-transformed animals." (PMID 25990313, 2015). "Chemokine CCL2 (MCP-1), one of the main chemo attractants for tissue monocytes/macrophages, might synergize with the other paracrine factors, further increasing macrophage recruitment to the tumor." (PMID 25599228, 2015). "Blocking monocyte entry into the lymph node and tumor through neutralization of the chemokine CCL2 or inhibition of colony-stimulating factor-1 receptor signaling prevented the generation of moDCs, the infiltration of tumor-specific T cells into the tumor, and antitumor responses." (PMID 26635798, 2015). "Expression of low level of chemokines such as CCL2 are suggested to contribute to the activation and transition of monocytes to macrophages, leading to expression of inducible-CCL2 during carcinogenesis and could serve as basis for localization and retention of macrophages in tumor microenvironment." (PMID 24473090, 2014). "Decreased levels of CCL2 therefore may have growth inhibitory activity on tumor cells." (PMID 24399973, 2013). "However, genetic ablation of CCL2 expression in LLC cells resulted in reduced tumor growth." (PMID 23967166, 2013). "Additionally, chemokines like CCL2 can recruit MDSC to tumor sites." (PMID 23935927, 2013). "Interestingly, tumor-bearing mice deposited CCL2 inside IVRs in the thymus." (PMID 22815949, 2012). "Since CCL2 can attract immunosuppressive Tregs and myeloid-derived suppressor cells to the tumor microenvironment, treatment with rVP1 may also help overcome the evasion of anti-tumor immune response." (PMID 21826248, 2011). "Furthermore, CCL2 stimulation drives PC-3 tumor cell diapedesis across a BMEC layer via PCNT1." (PMID 21776386, 2011). "Tumor-associated macrophages (TAM) derive mostly from circulating monocytes which are attracted into tumor sites, by locally produced chemotactic factors, such as CCL2, CCL5, CCL7, CCL8, CXCL12, vascular endothelial growth factor (VEGF), and macrophage colony stimulating factor (M-CSF)." (PMID 24212934, 2011). "In addition to the tumor-promoting activities of TNFα and IL-1β that have already been described, it is possible that these two cytokines also have functional interactions with CCL2 and CCL5, by that promoting disease course." (PMID 21486440, 2011). "(c) Signaling molecules also play a role, as the density of tumor-infiltrating T cells is negatively associated with expression of VEGF, B7-H1/PD-L1 and endothelin B receptor by tumors and positively associated with expression of the chemokines CXCL9, CCL21, CCL22, CCL2 and CCL5." (PMID 19641607, 2009). "Similarly, of the informative tumours that had 0–25% cells positive for CCL2 by ISH, four had LOH and two had no loss, while there were two tumours with greater than 26% of cells positive that both had LOH." (PMID 15900302, 2005). "Although both CSF-1 and CCL-2 can be targeted to the tumour cells themselves, the strong correlation of overexpression of these macrophage chemoattractants with macrophage recruitment and poor prognosis suggests that TAMs can play a major role in the progression of tumours to metastasis." (PMID 15164120, 2004). "Hypoxic tumor cells secrete chemotactic factors like VEGF, CCL2, CSF-1, and endothelins to attract monocytes/macrophages into oxygen-deprived regions." (PMID 41597210, 2026). "This review compiles current knowledge on the significance of lesser-known chemokines in MM tumor processes, including CXCL13, CCR2 ligands (CCL2 [MCP-1], CCL7 [MCP-3]), CCL4, CCL5 (RANTES), CCL17, CCL20, CCL27, CCL28, and CX3CL1 (fractalkine)." (PMID 41749925, 2026). "Conversely, M2 phenotype macrophages, induced by TGF-β, IL-4, IL-10, IL-13, colony-stimulating factor-1 (CSF-1), and C-C motif chemokine ligand 2 (CCL2), exert anti-inflammatory and tumor-supportive effects." (PMID 41590379, 2026).
tumor (continued). "Soluble mediators such as cytokines (IL-6, TNF-α), chemokines (CXCL12, CCL2), and immune checkpoints (PD-L1/PD-1, CTLA-4) further exacerbate the immunosuppressive state of HCC TME, forming a vicious cycle that facilitates tumor immune escape and progression." (PMID 41602547, 2026). "At the same time, miR-32-5p increases production of M1-type proinflammatory factors such as CD86, CCL2, tumor necrosis factor-α (TNF-α), and interleukin-6 (IL-6), thereby enabling macrophage polarization toward tumor-suppressive phenotype." (PMID 41608526, 2026). "Pathway analysis revealed activation of inflammatory and tumor microenvironment pathways, and upstream regulator analysis identified VEGFA and CCL2 as potential drivers." (PMID 41977309, 2026). "Previous research has demonstrated that CCR2, by binding to its ligand CCL2, drives the migration of CD14+ CD16+ monocytes from the peripheral blood to tumor sites, constituting a key pathway for immune cell recruitment to the TME." (PMID 41497137, 2026). "Peripheral blood monocytes can be recruited into the TME and differentiate into TAMs in response to tumor cell–secreted recruitment factors such as CSF1, CCL2, and CXCL12." (PMID 41426206, 2026). "In comparison, mouse fibroblasts from KPT tumors were enriched with cells highly expressing tumor-suppressing inflammatory CAF (iCAF) markers, including Has1, Ccl2, Il6, and Cxcl2 (clusters 1–3)." (PMID 41480763, 2026). "For example, CXCL9 and CXCL10 recruit effector T cells into the tumor via CXCR319, 20, promoting anti-tumor responses, while CCL2 recruits MDSCs through CCR2, thereby inhibiting immune responses." (PMID 41399390, 2026). "Our results suggest that N4BP1 controls multiple targets, such as CCL2, GM-CSF, CXCL8, and S100A2, to regulate multiple tumor malignant behaviors." (PMID 41513619, 2026). "Taken together, our results demonstrate a critical role of CCL2, GM-CSF, and CXCL8 in the establishment of an immune-suppressive tumor microenvironment." (PMID 41513619, 2026). "This increase positions CCL2 as a key player in obese condition among the target cytokines influenced by HIF‐1α, highlighting its crucial role in the tumor microenvironment." (PMID 41160815, 2026). "TAMs secrete chemokines such as CCL2 and CCL22, which attract immunosuppressive populations, such as myeloid-derived suppressor cells (MDSCs) and regulatory T cells (Tregs), into the tumor." (PMID 41597210, 2026). "Accumulating evidence indicates that inflammatory mediators-including CCL2, CCL3, CCL5, CXCL1, CCL20, TNF-α, IL-6, IL-8, and TGF-β-contribute to tumor growth, metastasis, immune modulation, and therapeutic resistance." (PMID 42245673, 2026). "Under stress, macrophages in the PMN release a variety of proinflammatory factors, such as TNF-α, MIP-2/CXCL2, MIP-1β/CCL4, CCL2/MCP-1, sICAM-1/CD54, and G-CSF, all of which promote tumor activity." (PMID 40109727, 2025). "By secreting specific cytokines and chemokines such as CCL2, ApoE, and TIMP1, it promotes the invasion and metastasis of tumor cells." (PMID 40495209, 2025). "Tumor cells with reduced Ccl2 production (Ccl2KD) showed attenuated metastatic outgrowth both using LLC1.1 and MC38-GFP tumor models, as shown for two independent clones, irrespective of mouse genotype." (PMID 39566333, 2025). "C-C motif chemokine ligand 2 (CCL2) is an important chemokine that recruits immune cells such as monocytes and macrophages to the tumor site." (PMID 41346595, 2025). "Elevated levels of CCL2 correlate with increased TAM accumulation in the TME, enabling tumor cells to evade immune surveillance." (PMID 40806751, 2025). "M2 macrophages secrete CCL2, which binds to CCR2 on tumor cells and activates the MEK–ERK–ELK1 axis, leading to increased SNAIL expression and a more invasive phenotype of GBC." (PMID 40564091, 2025).
tumor (continued). "As such, interruption of these interdependent nodes resulted in inhibition of paracrine factors that attract T cells (Ccl2, Ccl3) and those important for TAM support of tumor growth (Ccl4, Ccl5)." (PMID 41497446, 2025). "Above all, these results indicated that the CCL2/8-CCR2 axis and CXCL9/10-CXCR3 axis were involved in the anti-tumor immunity of the TTFields and anti-PD-1 treatment." (PMID 40098106, 2025). "In both genotypes (WT and KO) and treatment groups (Veh and Bc), CD163+ Toe-Macs were detected within tumor regions expressing high levels of NLRP3, IL-1β, TGF-β1, CCL2, IL-6, and PD-L1." (PMID 40794443, 2025). "Suppressing TAM activity by blocking the CCL2/CCR2–STAT3 pathway using siRNA or pharmacological agents enhances macrophage phagocytosis and inhibits tumor growth and metastasis." (PMID 41019045, 2025). "The release of pro-inflammatory chemokines and cytokines, such as IL-1, IL-2, IL-6, CCL-2, CCL-8, TNF-α and TGF-β, facilitate the recruitment of brain-resident immune cells to the tumour site." (PMID 41301734, 2025). "CCL2 forms a network and other factors (JAK) to collaboratively recruit and activate pro-inflammatory and pro-tumor immune cells." (PMID 41376630, 2025). "CAFs remodel the ECM and enhance tumor cell invasiveness by secreting cytokines (e.g., TGF-β, IL-6) and chemokines (e.g., CCL2, CXCL12), promoting angiogenesis and inducing EMT." (PMID 41430036, 2025). "Irradiated cancer cells secrete elevated levels of CCL2, enhancing MSC migration to tumor sites via CCR2." (PMID 40676710, 2025). "The cluster 6 monocytes were defined by high expression of multiple pro-tumor genes (IL1B, SERPINB2, CCL2, CXCL1, CXCL5, CXCL8, CCL3, CCL20)." (PMID 40176808, 2025). "Since CCL2/CCR2 signaling is a central signaling pathway that promotes monocyte recruitment into the TME, CCR2 inhibitors eliminate TAMs and inhibit tumor proliferation." (PMID 41008931, 2025). "In particular, the CCL2/CCR2 axis, the inhibition of the Ras/Raf/MAPK pathway, and the differential expression of miR-142, miR-146a, and miR-223 in tumor cells appear to play a critical role and have high clinical relevance." (PMID 40061903, 2025). "Consistent with the reduction of IL-1α, CCL2, and CCL3 in SHP2-silenced tumors, IHC revealed that tumor-infiltrating CD45+ hematopoietic cells and F4/80+ macrophages were significantly reduced in SHP2-silenced B16F10 tumors compared with controls." (PMID 40131370, 2025). "The anti-tumor drug 3,3’-diindolylmethane (DIM) activates NF-κB signaling in gastric cancer-TA-MSCs, enhancing their secretion of IL-6, IL-8 and CCL2, which in turn promotes cancer cell proliferation." (PMID 40676710, 2025). "Inhibitors of chemokines, such as CCL2 antagonists, can reduce TAM recruitment and attenuate tumor progression." (PMID 41310829, 2025). "Macrophages in the TME uptake lactate derived from the tumor, which further promotes the ENSA-K63la/SRC-pS12/STAT3-pY705 axis and increases CCL2 expression, enhancing the chemotactic effect on monocytes/macrophages." (PMID 39883522, 2025). "Cytokines, such as CCL-2, IL-6, IL-8, IL-10, IL-13, and TNF-α, exhibit tumor-specific secretion profiles." (PMID 40777043, 2025). "In parallel, CC chemokine ligand 2 (CCL2) drives monocyte chemotaxis via CCR2 signaling, while CCL5 contributes to TAM aggregation and enhances tumor invasion." (PMID 41142826, 2025). "Under in vitro conditions mimicking the elevated extracellular K+ concentration ([K+]e) characteristic of the tumor microenvironment (TME), CCL2 expression was markedly upregulated, and this increase was reversed by treatment with them in M2-MACs." (PMID 40806751, 2025). "The tumor immune microenvironment was remodeled by PPARG via recruiting and promoting the M2 polarization of macrophages through the CCL2/CCR2 signaling axis." (PMID 40183093, 2025). "In general, chemokines such as CCL2, CCL4, and CXCL10 can recruit cytotoxic T lymphocytes (CTLs) to the tumor and thus promote the anti‐tumor response." (PMID 40145607, 2025).
tumor (continued). "Other mechanisms include neutrophil secretion of cytokines such as CCL2 and CCL17, which modulate immune responses to promote tumour growth, progression, and drug resistance." (PMID 41451221, 2025). "By integrating these findings, Sun, Zhang, and colleagues identified a key mechanistic pathway in which elevated tumor glycolysis recruits monocytes and macrophages through the ENSA-K63la/SRC-pS12/STAT3-pY705/CCL2 axis." (PMID 40166931, 2025). "Concurrently, we observed marked upregulation of multiple pro-tumor factors, including MMP-11, IL-6, IL-1β, CCL5, and CCL2." (PMID 41276817, 2025). "Strategies that block CCL2 signaling (i.e., the CCL2-CCR2 axis) inhibit TAM recruitment and reprogram their functions to support anti-tumor immunity." (PMID 40806751, 2025). "Hypoxic tumor cells secrete chemokines (e.g., CCL2), hypoxia-inducible factors (HIF-1α, HIF-2α), and endothelin-2, which direct macrophage chemotaxis into the tumor core." (PMID 40422235, 2025). "Meanwhile, the YUMM1.7 model was more sensitive to chemotherapeutic treatment, secreted higher levels of chemokines CCL2, CXCL1, and CX3CL1, and showed higher infiltration of lymphocyte and myeloid subsets at the same tumor size." (PMID 40878826, 2025). "In glioblastoma, LDHA activates the ERK-YAP1/STAT3 axis, upregulating CCL2 and CCL7 to recruit macrophages, which in turn deliver LDHA to tumor cells via extracellular vesicles, forming a tumor-macrophage symbiotic loop that drives progression." (PMID 40734168, 2025). "At least, in this study, we found a positive correlation between the number of tumor infiltering-CD68 + macrophages and CCL2, a chemokine able to recruit monocytes/macrophages at the site of inflammation." (PMID 40064752, 2025). "A positive correlation was detected between the number of tumor-infiltering CD68 + macrophages and the CCL2 intensity score (p = 0.008, r = 0.695)." (PMID 40064752, 2025). "CCL2 Monocyte Chemoattractant Protein-1 (MCP-1) is a member of the C-C chemokine family, and high levels of CCL2 induce polarization of macrophages to the tumor-promoting phenotype of TAMs." (PMID 39996747, 2025). "Consistently, ZEB1-dependent CCL2 abundance correlated with CTL influx and tumor cell killing in metastatic lung colonies." (PMID 40595293, 2025). "The mechanisms through which CCL2 shapes the TIME are tightly regulated by tumor cells, tumor-infiltrating immune cells, and the tumor stroma." (PMID 40940890, 2025). "TTFields enhance the effectiveness of anti-PD immunotherapy by improving CD4+ T cells and CD8+ T infiltration via inducing ICD to increase CCL2/8 and CXCL9/CXCL10 expression of tumor cells." (PMID 40098106, 2025). "Studies in mouse models have demonstrated the crucial role of CCL2 and other chemokines in TAM recruitment.1028 Tumor cells release CCL2, which attracts cells expressing the CCR2 receptor to the tumor site." (PMID 40055311, 2025). "For instance, through C-C motif chemokine ligand 2 (CCL2) signaling, the M2 subtype can induce epithelial-mesenchymal transition (EMT), which facilitates tumor growth and invasion." (PMID 40918452, 2025). "At the same time, upregulation of Ccl2+ in fibroblasts and a more immunomodulatory macrophage phenotype was observed in CAR-T-treated tumors, indicating a tumor adaptation mechanism." (PMID 40568084, 2025). "This polarization promotes the secretion of pro-inflammatory cytokines, such as interleukin-6 (IL-6), interleukin-8 (IL-8), and C-C motif chemokine ligand 2 (CCL2), thereby activating effective anti-tumor immunity." (PMID 39893499, 2025). "Functional assays show that SPON2 promotes OS cell proliferation, migration, invasion, and angiogenesis by enhancing the secretion of IL10, CCL2, and CSF1, which leads to M2 macrophage polarization and an immunosuppressive tumor microenvironment." (PMID 40730813, 2025).
tumor (continued). "Treatment of mesenchymal stromal cells (MSCs) isolated from lung cancer patients led to a significant reduction in the production of IL-6 and chemokines like CCL2, and CCL3 that play key roles in tumour progression and immune modulation." (PMID 40943351, 2025). "The WB test results revealed that the expression levels of JAK/STAT3/CCL-2 pathway-related proteins p-JAK/JAK, p-STAT3/STAT3 and CCL-2 were significantly cut down in the tumor cells of the sh-OSMR group relative to the sh-NC group." (PMID 40161370, 2025). "It has also been reported in various solid tumors that CCL2 secreted by CAFs recruits MDSCs via the STAT3-CCL2 signaling pathway, thereby promoting tumor growth." (PMID 40890855, 2025). "The CCL2/CCR2 axis, which regulates monocyte recruitment and differentiation into TAMs, has been effectively targeted to disrupt TAM function and enhance tumor sensitivity to immunotherapy." (PMID 40098971, 2025). "In a KRAS-driven lung cancer model, the SASP secreted by senescent macrophages includes chemokines such as CCL2, CCL8, CCL7, CCL24, and CXCL13, which are involved in tumor cell metastasis." (PMID 39781471, 2025). "We found that knockdown of AXL significantly reduced the expression of CCL-2, CSF-1, IL-10, and TGF-β cytokines in ccRCC tumor cells." (PMID 41029360, 2025). "MCP1 (CCL2) is a small cytokine that is closely related to hypoxia and has a positive effect on tumor development." (PMID 40430040, 2025). "It is also possible that inhibition of a tumor–MDSC interaction was interrupted after BRD4 inhibition, as additional tumor-secreted soluble factors, including chemokines (CCL2, CXCL3, and CXCL5), were all reduced after BRD4 inhibition in vitro." (PMID 40762981, 2025). "In B-lymphoma cells and murine models, the muting of CREBBP/EP300 in tumor cells resulted in polarization of TAMs towards the M2 phenotype by activating the NOTCH signaling pathway and downstream CCL2/CSF1 axis." (PMID 40216772, 2025). "Further, when stratified SCC patients according to α3 Laminin expression it has been demonstrated that lower α3 Laminin expression confers tumor cells a more invasive behavior and that these cells release higher amount of CCL-2/MCP-1 and IL-13." (PMID 40868818, 2025). "Some studies have suggested redundant roles for CCL2 and CCL4 so we expected that our CCR2 and CCR5 armored CAR-T cells would be equivalent in terms of in vitro and in vivo tumor-directed homing and efficacy." (PMID 41424784, 2025). "Consistent with previous reports on other tumor-targeting IgE antibodies, 16 20 anti-HER2 IgE cross-linking, also stimulated upregulation of CCL2, and of the anti-inflammatory mediator IL-10." (PMID 40074330, 2025). "Cytokines and chemokines secreted by tumor cells, such as IL10, CCL2, and CSF1, are key drivers of TAM plasticity within the pro-tumor microenvironment." (PMID 40730813, 2025). "Along with the acquisition of single-cell RNA-sequencing data, the relationship of each clustering target, CCL2-positive fibroblasts, focused on the PPIA-BSG pathway, which plays a critical role in connecting LGALS3-high tumor cells." (PMID 40600063, 2025). "The maturation and antigen presentation functions of TIDCs can be seriously impeded by the high levels of VEGF, CCL2, CXCL1, and CXCL5, released by CAF-induced tumor cells." (PMID 40805183, 2025). "M2-polarized TAMs dominate the immunosuppressive tumor microenvironment (TME) and promote EMT through cytokines such as TGF-β, IL-6, and CCL2." (PMID 40304000, 2025). "Topical delivery of CCL2 siRNA via Ca-TAT nanocomplexes can achieve efficient and durable gene silencing in tumor cells with minimal effect on normal tissues." (PMID 41341593, 2025). "These included LGR5 as a stem cell and regeneration mRNA marker, SNAIL and TWIST1 as markers of epithelial–mesenchymal transition; and IL-8, CCL2, and COX2 as pro-inflammatory tumor microenvironment markers." (PMID 40476597, 2025).